IL10 (interleukin 10)
Diseases named in the same sentence as IL10 in open-access papers (continued):
Sharing a sentence is not in itself a finding about the gene and the disease.
atherosclerosis (continued). "In this regard, there are promising studies regarding the beneficial role of specific anti-inflammatory molecules, such as IL-10, in atherosclerosis, but they need to be further studied and are still not clinically used in the treatment of patients." (PMID 33153204, 2020). "In addition, anti-inflammatory cytokines IL-10 and insulin sensitizing hormone ADPN have been shown to have anti-atherosclerosis effects." (PMID 32231564, 2020). "Additionally, increasing IL-10, IL-4, IL-13, and TGF-β and reducing IL-1β, Il-6, TNF-α, CCL3, CCL4, and CCL5 can slow the progression of atherosclerosis." (PMID 32346605, 2020). "It is therefore speculated that the imbalance of IL-10 and TNF α may be relevant to the pathological development of atherosclerosis and heart failure." (PMID 32670064, 2020). "Highly expression levels of IFN-γ and IL-17A are shown in the animal model of atherosclerosis, while IL-10 and TGF-β1 have been proven to act as key anti-inflammatory agents in vivo and content elevation of IL-10 and TGF-β1 effectively attenuate the expansion of atheroma plaques." (PMID 31379468, 2019). "Upregulation of IL-10 expression with a concomitant decrease in the production of TNF-α and IL-18 was put forward as a direct anti-inflammatory mechanism of IL-37 mediated amelioration of atherosclerosis and CAC." (PMID 29641433, 2018). "Tregs can slower development of atherosclerosis by inhibiting immune overactivity of effector T cells and secrete major anti-inflammatory cytokines, such as interleukin-10 (IL-10) and transforming growth factor (TGF-β), which are able to reduce inflammatory response in atherosclerosis." (PMID 26063978, 2015). "IL-10 concentration was lower in control subjects with significant atherosclerosis (median 0.60 pg/ml) than those without (median 1.00 pg/ml) (p = 0.05)." (PMID 17328808, 2007). "Furthermore, in the estrogen replacement and atherosclerosis (ERA) study, an elevated baseline level of IL-10 was correlated with cardiovascular outcomes in post-menopausal women with angiographically proven coronary artery disease (n = 309, follow-up of 3.2 years)." (PMID 39199367, 2024). "In our human plaque tissue slice experiments, we observed decreased the secretion of TNFα, IL-8 and IL-10 after STAT5 inhibition, suggestive of a pro-inflammatory activity of STAT5 in plaque and identifying macrophage STAT5 as a candidate for intervention in human atherosclerosis as well." (PMID 37920458, 2023). "By inputting hsa-miR-18a-5p, IL-10, CRP, VEGF-D, thrombomodulin, along with glucose to demonstrate a diabetic state into IPA software, miR-18a-5p was predicted to enhance the progression of atherosclerosis, infarction, and inflammatory response whilst inhibiting angiogenesis and blood coagulation." (PMID 36140236, 2022). "Meanwhile, growing evidences have confirmed that, some inflammatory cytokines, such as IL-10, IL-1β, IFN-γ and TNF-α, may be responsible for the pathogenesis of atherosclerosis because these cytokines can result in the adhesion of leukocytes to vascular endothelium and foam cell formation." (PMID 32169038, 2020). "Lack of IL-10 impacts on the development of atherosclerosis in mice." (PMID 29329335, 2018). "In this group of genes we observed correlation between the cytokine IL10 and ELANE, an elastin protease known to degrade elastic fibers as elastin; indicating that elastin degradation and immune response process are common interacting regulatory mechanisms in atherosclerosis." (PMID 25503069, 2014). "EAT secretes various proinflammatory adipokines like interleukin (IL)-1, IL-6, IL-8, IL-10, tumor necrose factor (TNF) α, leptin, macrophage chemoattractand protein 1 (MCP-1), type I plasminogen activator inhibitor (PAI-1), resistin that provide a metabolic milieu that promotes atherosclerosis." (PMID 23133630, 2012). "Several lines of evidence suggest that IL-10 may have a therapeutic potential in atherosclerosis, but its mechanisms of action have not been clarified." (PMID 21673935, 2011).
atherosclerosis (continued). "In addition, Bregs dampen inflammation, e.g., via IL-10 production, and may thus behave atheroprotective, although another study could not confirm a role of B-cell-derived IL-10 in atherosclerosis." (PMID 40986007, 2025). "One can hypothesize that AhR activation would abrogate the adverse role of KYNA in atherosclerosis development in IDO-deficient mice because it is known, for example, that AhR promotes IL-10 expression in inflammatory macrophages via the nongenomic Src–STAT3 signaling pathway." (PMID 39000041, 2024). "So, RAB5A may be involved in the pathogenesis of atherosclerosis by changing the proliferation and migration function of endothelial cells through some cytokines and/or signaling pathways, such as the interferon response, Notch signaling pathways, VEGFR2, VE-cadherin, NOS3, and IL-10." (PMID 35059464, 2022). "In addition, important immune regulators essential to inflammation including IL-10, transforming growth factor β (TGF-β), and lipid mediators which include lipoxins, resolvins, protectants, methylene resins, and prostaglandins are all closely related to the development of atherosclerosis." (PMID 32733941, 2020). "In addition, atherosclerosis is considered to be a chronic inflammatory disease of the large and medium arteries, with changes in pro-inflammatory cytokines such as tumor necrosis factor-alpha (TNF-α),interleukin (IL)-6, and IL-1β, and anti-inflammatory cytokines including IL-10." (PMID 32231564, 2020). "Although it has been reported that IBD is closely related to the pathogenesis of atherosclerosis-related CVD (ASCVD) in some cases, whether the link between IBD and CVD is attributable to the mutations of IL-10 or its receptor has not been carefully explored." (PMID 36110841, 2022). "Similarly, the stimulation of IL-10 production by VitD/Dexa in non-cDC non-B APC (left) is also interesting, since monocyte-derived DC appear to be important during atherosclerosis development and tolerogenic plasmacytoid DC are atheroprotective." (PMID 32395119, 2020). "Our finding, therefore, suggests a role for IL-10 in controlling food intake and REE independent of exercise that deserves further exploration, also in light of the fact that IL-10 profoundly reduced lipid accumulation in the vessel wall, preventing atherosclerosis." (PMID 26193314, 2015).
Stroke (302 papers, 2007 to 2026). Sudden impairment of blood flow to a part of the brain due to occlusion or rupture of an artery to the brain. "Patients with higher cholesterol, LDL, SBP, and DBP levels and lower HDL levels, together with the presence of IL-1β (rs16944) and IL-10 (rs1800896) polymorphisms, were more likely to develop stroke." (PMID 40369205, 2025). "Regarding IL-10 (rs1800896), the genetic dominant model (GA + AA vs. GG) was only significantly associated with troubles in chewing and swallowing among stroke patients (p = 0.018)." (PMID 40369205, 2025). "Previous results revealed that both homozygotes AA and heterozygotes AG genotypes of IL-10–1028 A/G were more frequent in stroke patients than healthy individuals, and the A allele was thought to be a risk contributor to IS in the Turkish population." (PMID 40369205, 2025). "For IL-10 gene polymorphism, the heterozygous GA genotype was identified in 93% of stroke patients, higher than in controls (47.3%)." (PMID 40369205, 2025). "Clinical studies have revealed that decreased IL-10 following stroke is associated with a decline in neurologic condition." (PMID 38421829, 2024). "Lower levels of IL-10 post-stroke have been linked to an increased risk of PSD, emphasizing the protective role of anti-inflammatory cytokines in this context." (PMID 38377025, 2024). "Conversely, IL-10, an anti-inflammatory cytokine, is associated with stroke outcomes and quality of life, acting as a protective factor against PSD." (PMID 38377025, 2024). "Clinical studies showed that, low levels of IL-10 are associated with a higher risk of hemorrhagic transformation or neurological deteriorations, whereas high levels with an increased risk of stroke-associated infections." (PMID 36745280, 2023). "IL-1β has been associated with exacerbation of injury in stroke and has been implicated in the pathogenic processes associated with a number of central nervous system disorders, while IL-6 and IL-10 have been found to be neuroprotective." (PMID 36969226, 2023). "Specifically, in stroke, the adoptive transfer of B cells from WT mice reduced infarct volumes compared to IL-10-deficient B cells, confirming additional IL-10-mediated neuroprotection following stroke." (PMID 36446955, 2022). "Humans with low IL-10 serum levels had an increased risk of stroke and type 2 diabetes and are associated with the metabolic syndrome." (PMID 35889872, 2022). "Deficiency in IL-10 reduced the neuroprotective effects of adoptively transferred CD8+ TRLs in CD8+ TRL–depleted mice 3 days after stroke." (PMID 35912857, 2022). "In human patients, low plasma levels of IL-10 in the first hours after stroke onset were associated with worse neurological deficits at 48 h." (PMID 35008440, 2021). "In conclusion, increased IL-6 and reduced IL-10 concentrations are present in the early stroke period and are associated with a degree of neurological deficit and stroke outcome." (PMID 33922467, 2021). "Neutralization of IL-17A following stroke reversed the worse outcome in IL-10 deficient mice and intracerebral treatment with recombinant IL-10 revealed that IL-10 controlled IL-17A positive lymphocytes in ischemic brains." (PMID 34772416, 2021). "IL1-ra was studied along with IL-10, cortisol, and lymphocyte count, and only IL-1-ra was independently associated with the risk of infection in 112 stroke patients." (PMID 34092245, 2021). "Our study shows that Qi deficiency and blood stasis of CHD and stroke includes some inflammatory factors: IL-10, FOXP3, cell apoptosis, differentiation, and proliferation." (PMID 32670064, 2020). "In stroke patients, higher plasma level of IL-10 is associated with the increased risk of infections and lack of response to preventive antibacterial therapy." (PMID 31906994, 2020). "This was associated with 2.7-fold greater lung expression of Il-10 mRNA (P = 0.006), whereas in contrast to brain, IL-37 mRNA in the lungs tended to be reduced by stroke (P = 0.075)." (PMID 31061403, 2019).
Stroke (continued). "Increased production of IL-10, the prototypic anti-inflammatory cytokine, in delirious patients supports an idea that post-stroke immunodepression is linked to delirium." (PMID 29669581, 2018). "The temporal IL-10 profile appears to be different between those that develop stroke-associated infection." (PMID 28659854, 2017). "We proposed that stroke-induced activation of iNKT cells mediate an immunosuppressive response, via the release of IL-10, and render the patient with greater susceptibility to infection." (PMID 28154551, 2017). "Systemic IL-10 overexpression in stroke-prone spontaneously hypertensive rats reduces the incidence of stroke, decreases stroke-associated symptoms, and improves survival." (PMID 28659854, 2017). "One other study in an Eastern Finland population showed that IL-10 plasma concentration independently correlates with cardioembolic high-risk sources, suggesting its usefulness in improving diagnosis of stroke etiology." (PMID 28659854, 2017). "Both clinical and animal studies show that a multitude of cytokines such as IL-6 and IL-10 are activated after stroke, induce stroke-associated immunodepression, and greatly increase the risk of infection." (PMID 27409177, 2016). "The present study unveiled the existence of an immunopathological outcome underlying chagasic patients condition that involves an imbalanced expression of IL-10, FoxP3 and iNOS, which increases the risk of stroke or death." (PMID 27115869, 2016). "In this pilot study we investigated the distribution of Th17 and Treg cells and serum levels of Treg-derived IL-10 in stroke patients to reveal a possible mechanism underlying PSF." (PMID 26166952, 2015). "In ischemic stroke, an excessive IL-10 response contributes to post-stroke immunosuppression, increasing the risk of post-stroke infection and poor outcomes." (PMID 26462256, 2015). "IL10 forms part of an inflammatory genetic profile and elevated levels of IL10 post stroke have been implicated in severe neurological impairment and major adverse clinical outcomes." (PMID 23505425, 2013). "In those > =85 years, lower IL-10 production in lipopolysaccharide-stimulated whole-blood samples have been shown to be significantly associated with increased incident fatal stroke." (PMID 24040186, 2013). "Additionally, alterations in regulatory T cell (Treg) populations and dysregulated cytokine signatures—particularly elevated interleukin-6 (IL-6) and interleukin-10 (IL-10)—have consistently been linked to increased stroke risk and AF recurrence." (PMID 41156185, 2025). "Conversely, elevated IL-10 levels in the subacute phase (days 2–7) may indicate stroke-induced immunosuppression (SIS), increasing the risk of infections such as pneumonia and urinary tract infections." (PMID 40869247, 2025). "Regarding IL-10, GA genotype, A allele, over dominant (GG + AA vs. GA), and dominant (GG vs. GA + AA) genotyping models in patients, they show highly significant differences from controls that increased the risk of stroke." (PMID 40369205, 2025). "For instance, the elevated levels of IL-17A following a stroke are associated with reduced IL-10, and the suppression of IL-17A may enhance the outcomes in mice lacking IL-10." (PMID 39881806, 2024). "By reducing the body’s inflammatory response, IL-10 reduces the risk of stroke." (PMID 36793730, 2023). "IL-10 is a pleiotropic immunoregulatory cytokine with cytoprotective effects having a crucial role in the development of the anti-inflammatory milieu associated with tissue repair, i.e., after stroke." (PMID 35585424, 2022). "Furthermore, IL-10 exerts neuroprotective effects and a diminished IL-10 level is associated with increased stroke risk." (PMID 35283778, 2022). "We demonstrated that IL-10 overexpression by this approach substantially modulated microglia gene expression by down-regulation of microglial gene signature associated with phagocytosis of synapses correlating with functional recovery after stroke." (PMID 36512388, 2022).
Stroke (continued). "However, stroke patients are susceptible to infection as a result of stroke-induced immunosuppression, and elevated serum IL-10 levels have been identified as an independent predictor of post-stroke infection." (PMID 35173738, 2022). "Elevated IL-10 levels may be associated with higher incidence of post-stroke urinary tract infection, leading to poorer recovery after ischemic stroke in women." (PMID 35173738, 2022). "An important finding in this study was the observation that IL-10 overexpression in T cells modulated microglial genes involved in the complement pathway, phagocytosis, and synaptic pruning and was associated with a better functional outcome after stroke." (PMID 36512388, 2022). "Peripheral IL-6 and IL-10 levels were linked to worsened or improved stroke outcomes, respectively." (PMID 34966269, 2021). "Similarly, another study also reported that reduced IL-10 concentrations were associated with a degree of neurological deficit and poor stroke outcome." (PMID 34336007, 2021). "Leukopenia with reduced IL-10 is associated with better outcome in animal models of brain injury and in human adult stroke patients; the observed functional immune compromise may be due to bone marrow suppression and reduced leucocyte release." (PMID 29471782, 2018). "The association between serum IL-10 level and infections in stroke patients has been reported." (PMID 27682880, 2017). "At the clinical level, lower IL-10 levels increased stroke risk." (PMID 28936196, 2017). "In other studies, low IL-10 levels are associated with acute neurologic decline post-stroke." (PMID 28659854, 2017). "However, we found a positive correlation between plasma levels of IL-10 and iNKT cell activation at stroke onset, suggesting that the production of IL-10 in stroke patients is likely to associate with the activation of peripheral iNKT cell." (PMID 28154551, 2017). "Similarly, subjects with low IL-10 production in response to LPS stimulation have a higher risk for fatal stroke." (PMID 28659854, 2017). "However, the NIHSS at stroke onset showed an independent positive association only with IL-6 and IL-10 on day 3 (all p < 0.05)." (PMID 27682880, 2017). "Increased CD45 expression in the inhibitor group (as compared to controls) at 14 days after stroke may be associated with prolonged upregulation of IL-10, since IL-10 was found to activate CD45 protein tyrosine phosphatase." (PMID 27829437, 2016). "In addition, there was a female-specific association between higher IL-10 levels and stroke severity on admission (p = 0.049), composite negative outcome at 3 (p = 0.035) and 12 months (p = 0.022), and post-stroke urinary tract infection (p = 0.003)." (PMID 26462256, 2015). "Higher IL-10 levels measured at 24 h post-stroke were associated with poor acute and long-term outcomes in females only, which may be in part due to the older age of females in this cohort compared to males." (PMID 26462256, 2015). "In experimental models of brain ischemia, post-stroke infections have been associated with the activation of the autonomic nervous system and neuroendocrine pathways, which activate anti-inflammatory signaling pathways, including IL-10." (PMID 26462256, 2015). "Thus, this study was likely underpowered to detect an independent association between IL-10 and stroke outcomes by sex." (PMID 26462256, 2015). "Also, increased IL-10 levels within 24 h were associated with infection in patients from the Early Systemic Prophylaxis of Infection after Stroke (ESPIAS) trial, a randomized clinical trial using preventive antibacterial treatment with levofloxacin." (PMID 25613713, 2015). "Clinically, lower IL-10 plasma levels have been associated with increased risk of stroke." (PMID 24499655, 2013). "However, there is a dearth of information on the association between serum IL-10 and stroke in the general population." (PMID 24040186, 2013). "Stroke patients who produce high levels of IL-10 may be more susceptible to infection." (PMID 36793730, 2023).